ALB (albumin)
Diseases named in the same sentence as ALB in open-access papers (continued):
Sharing a sentence is not in itself a finding about the gene and the disease.
cancer (continued). "Glasgow Prognostic score may thus reflect both the presence of an ongoing systemic inflammatory response (C-reactive protein) and the progressive nutritional decline (albumin) of the patient with advanced cancer." (PMID 16479253, 2006). "The clinical validation of albumin as an effective drug carrier is exemplified by the success of nab-paclitaxel (albumin-bound paclitaxel, Abraxane®), which has demonstrated superior efficacy and reduced toxicity compared with solvent-based paclitaxel in multiple cancer types, including TNBC." (PMID 41489768, 2026). "After treatment with 20 μmol/L pumpkin 2S albumin, the survival rates of these cancer cell lines were significantly reduced, among which MCF-7 cells were the most sensitive, and their cell viability could be significantly inhibited at a concentration of 5 μmol/L." (PMID 41300124, 2025). "However, to the best of our knowledge, no studies have yet investigated the association between laryngeal cancer and the haemoglobin–albumin–lymphocyte–platelet (HALP) score, a widely studied prognostic parameter in previous research on inflammatory diseases and various cancer types." (PMID 40629172, 2025). "Furthermore, the internalization and nuclear localization of the complex in cancer cells—mediated by both integrin- and albumin-related uptake—could enable localized radiotoxicity through the short-range Auger electron emission of 64Cu." (PMID 40867175, 2025). "As albumin plays an important role in binding to various substances, their transport, solubilization, and stabilization, and gamma gap is related to latent inflammation, cancer, autoimmune diseases, their interction may exist." (PMID 41248155, 2025). "This growing interest has led to the publication of numerous studies exploring different aspects of albumin, including its structural characteristics, pharmacokinetics, and potential use as a drug carrier or therapeutic agent in conditions like liver cirrhosis, cancer, and cardiovascular diseases." (PMID 40699702, 2025). "Low‐serum albumin levels, impaired performance status (ECOG‐PS ≥ 2), cancers with known high mortality rates, and advanced stage at diagnosis (Stage III or IV) also maintained a positive association with mortality and cancer progression in all regression models." (PMID 40116494, 2025). "Together, these findings suggest that targeting lipid scavenging could be a more effective therapeutic approach to target the increased lipid demand of proliferating cancer cells, though any such strategy would have to overcome the redundancy of alternate albumin-bound lipid sources." (PMID 40027810, 2025). "Furthermore, low ALB levels are linked to poor nutritional status, inflammation, and negative clinical outcomes in cancer survivors." (PMID 40018412, 2025). "Additionally, decreased albumin levels are a marker of poor cancer prognosis." (PMID 39831739, 2025). "Abnormal results in six different blood tests increase in frequency from 7 months before cancer diagnosis in patients with abdominal symptoms, suggesting they could be early signals of undetected cancer, particularly raised platelets, raised inflammatory markers and low albumin." (PMID 39799273, 2025). "Moreover, albumin has antioxidant properties, which can inhibit cancer progression." (PMID 40357031, 2025). "Instead, mortality and cancer progression were associated with older age, male sex, diagnosis of T2D, worse performance status, ever‐smoker status, heavy alcohol drinking, lower BMI or %BMI, and higher inflammatory status (including a higher SIRI and lower serum albumin concentrations)." (PMID 40116494, 2025). "In cancer patients, the largest increases from baseline were raised platelets in males with abdominal pain (increased 33-fold), raised white blood cell count in males with abdominal bloating (increased 37-fold) and low albumin in females with either symptom (increased 22–41 fold)." (PMID 39799273, 2025).
cancer (continued). "A low level of albumin may also reduce the tolerance of systemic anti-cancer treatment." (PMID 40416620, 2025). "The primary component of serum proteins, serum ALB, has been shown to have a role in the emergence of systemic inflammation and may be utilized extensively to evaluate the nutritional status and severity of cancer patients’ diseases." (PMID 40842988, 2025). "Hence, more freely soluble ALB would be available to induce its anti-cancer effect." (PMID 40978467, 2025). "Although it is known that albumin and calcium tests may be useful in identifying patients with a higher-than-average cancer risk, the evidence is limited and does not take into account patient ethnicity." (PMID 40941010, 2025). "Moreover, chemotherapy may lead to the deterioration of cancer patients’ body systems, thus impairing their ability to synthesize albumin." (PMID 41304781, 2025). "Furthermore, ALB levels serve as a prognostic indicator in cancer progression." (PMID 40013138, 2025). "Moreover, high serum albumin levels may provide an antiproliferative effect in cancer cells in vitro." (PMID 38913646, 2024). "Furthermore, in addition to NIR and MRI imaging, computer X-ray tomography and photoacoustic image-guided PDT and PTT therapy for cancer using albumin NPs have also been widely studied in recent years, which may catch the attention of future researchers." (PMID 39070787, 2024). "Furthermore, a nonlinear negative association was observed between serum albumin levels and the risk of cancer mortality." (PMID 38500655, 2024). "For all cancers combined, blood test abnormalities known to increase the risk of cancer above the 3% threshold recommend by the National Institute for Health and Care Excellence (NICE) for urgent investigation are low albumin, raised platelets, raised calcium, and raised inflammatory markers." (PMID 38730644, 2024). "Of these metabolites, total lipids in VLDL, total cholines, omega-3 fatty acids, tyrosine, glucose, citrate, creatinine, free cholesterol in IDL, and total lipids in large HDL had significant negative associations with overall cancer risk, with albumin being the only exception." (PMID 39003294, 2024). "Therefore, monitoring serum albumin levels in cancer patients could provide valuable insights into both their nutritional risk and the effectiveness of ongoing treatments." (PMID 39807216, 2024). "Therefore, reduced albumin levels may indirectly affect the prognosis of cancer by promoting the development of other diseases." (PMID 38500655, 2024). "Thus, albumin may improve cancer survival by lowering free cholesterol and fatty acids in the blood through its binding effect." (PMID 38500655, 2024). "For all cancers combined, the following blood test abnormalities increase the risk of cancer above the 3% threshold recommended by the National Institute for Health and Care Excellence (NICE) for urgent investigation: low albumin, raised platelets, raised calcium, and raised inflammatory markers." (PMID 36624489, 2023). "As a combination of albumin and globulin, the albumin-to-globulin ratio (AGR) reflects both nutritional status and inflammatory response, which has been reported to be associated with the prognosis of several cancers.We suggest that AGR is a credible predictive parameter for several reasons." (PMID 37491191, 2023). "Decreased serum albumin reflects lean tissue loss, an increased systemic inflammatory response and may be a negative prognostic factor for survival in various primary cancer diagnoses." (PMID 37906352, 2023). "The Glasgow Prognostic Score (GPS), which combines C-reactive protein and albumin levels that reflects the systemic inflammation status and the nutrition status of the patient, respectively, has been reported to be a reliable tool for assessing the status of cancer cachexia." (PMID 36674837, 2023). "Therefore, serum CRP and albumin are considered as interrelated serum biomarkers that may reflect host and cancer status, respectively." (PMID 37333829, 2023).
cancer (continued). "Thus, albumin levels can serve as good indicators of nutritional status and cancer prognosis." (PMID 37492594, 2023). "Furthermore, changes in CAR, composed of CRP and albumin, may be more sensitive to patient and/or cancer conditions than CRP or albumin alone." (PMID 37333829, 2023). "This is could be due to advanced stage cancer cells increased uptake of serum albumin." (PMID 36869395, 2023). "In exploring the mechanism behind the enhanced cancer cellular uptake of the prepared conjugates, we thought that the native receptors of the proteins may play very limited roles, as albumin and RBD bind to different receptors (e.g., SPARC/gp60 for albumin and ACE2 for RBD)." (PMID 36684090, 2023). "Thus, low albumin levels in patients with cancer can be attributed to various factors." (PMID 36924334, 2023). "In addition, significant changes in other readily accessible inflammatory markers comprising acute phase reactants, primarily as low serum albumin level and increased serum globulins and C-reactive protein (CRP), were observed as a result of cancer-associated inflammation." (PMID 36983756, 2023). "However, some studies in various type of cancer observed that higher hemoglobin and albumin levels, in line with the incidence of CIN in the first cycle, were significantly associated with better overall survival and disease-free survival, and offers insights into patient's nutritional status." (PMID 38414951, 2023). "Furthermore, lymphocyte–CRP and CRP–albumin ratios are prognostic predictors for many cancers." (PMID 37794336, 2023). "Similarly, the Glasgow Prognostic Score (GPS) based on CRP and albumin levels might be a useful indicator of performance status and survival in cancer patients." (PMID 37816885, 2023). "Prognostic nutritional index (PNI), which is calculated using the albumin level reflecting nutritional status and lymphocyte count reflecting immune status, is useful in showing nutritional and immunological status related to survival and prognosis in many cancers." (PMID 37685501, 2023). "While a 2014 study showed that a panel consisting of ALB, CA19-9, CRP, and IL-8 had the highest diagnostic value for distinguishing PDAC from controls, with this panel proving to be effective in identifying other cancers, such as breast, cervical, colorectal, prostate, and lung." (PMID 36969742, 2022). "Natural polymers like alginic acid, albumin, chitosan, gelatin, polypeptides and synthetic polymers like polycaprolactone, polylactide-co-glycolide, and polylactic acid are some of the polymers used in the development of polymer-based nanoparticles to treat cancer." (PMID 36330493, 2022). "Besides the traditional TNM system, accumulating evidence has demonstrated that hematological parameters, including neutrophil, lymphocyte, monocyte, platelet counts, serum hemoglobin, albumin, and fibrinogen, play an important role in cancer progression and metastasis." (PMID 35020581, 2022). "BMI, rather than serum albumin, was associated with OS in patients who underwent PD for cancer." (PMID 35773692, 2022). "In addition, reduced serum albumin is often closely related to poor outcomes in cancer patients." (PMID 35606690, 2022). "Moreover, a high C-reactive protein (CRP)/albumin (ALB) ratio (CAR) was found to be associated with poor outcome of cancer patients, and this marker could be used as a predictor of poor cancer prognosis." (PMID 35372394, 2022). "In fact, after adjusting for age, sex, and cancer, a GNRI value below 92 was significantly associated with worse MNA® scores, and lower values for the following: weight, BMI, mid-arm circumference, calf circumference, and serum levels of total protein, albumin, and prealbumin." (PMID 36432512, 2022).
cancer (continued). "Remarkably, many proteins that frequently display quantitative changes in cancer patients, such as cytokines/chemokines, extracellular matrix proteins, coagulation factors, complement factors, immunoglobulins, and albumin, can interact with EVs after their release and change their composition." (PMID 36139375, 2022). "Moreover, albumin maintains the regularity of sex hormones against cancers." (PMID 35392843, 2022). "Hence, the combination of LYs and serum ALB can better predict the outcomes of cancer patients." (PMID 35990994, 2022). "CRP/Alb, obtained from the combination of CRP and albumin levels, can reflect the inflammation and nutritional status of cancer patients and provide a fully integrated view of the effects of inflammation and low nutritional status on the prognosis of cancer patients." (PMID 36107592, 2022). "However, some work has shown that quercetin can enhance the bioavailability of curcumin by increasing its uptake into human carcinoma cells, which might be related to an ALB (albumin)-binding interaction." (PMID 36497321, 2022). "The remarkable antitumoral effect obtained highlights the potential of albumin nanocarriers for gene therapy in combination with other therapies, namely radiotherapy, magnetic field stimulated targeting, and molecular targeted therapy, for the treatment of cancer." (PMID 34298666, 2021). "Thus, a low serum albumin concentration usually predicts poor prognosis in patients with cancer." (PMID 34645392, 2021). "Although adjuvant chemotherapy after complete resection is not currently recommended for pStage IA NSCLC, future improvements in techniques for detecting micro cancer cells, including decreased albumin, might allow the selection of cases that would benefit from adjuvant chemotherapy." (PMID 34473762, 2021). "One previous study developed a risk score to predict cancer in a cohort of 256 patients referred for the investigation of UWL (AUC 0.90 (95% CI 0.88 to 0.92)) including the following: age ≥80 years, white blood cells, albumin, alkaline phosphatase, and lactate dehydrogenase." (PMID 34464384, 2021). "However, with limited follow‐up duration, the albumin concentration used in this analysis was at one single time point, and changes of cancer risk along with albumin concentrations were not analyzed." (PMID 34041866, 2021). "In conclusion, we found that two routinely measured inflammatory biomarkers (albumin and CRP) and the scores calculated therefrom (the GPS, the mGPS, and the CRP/albumin ratio) add prognostic value to conventional demographic, oncologic or frailty risk factors when considering older cancer patients." (PMID 34944774, 2021). "It is a composite index that factors in changes in patients' ideal body weight, present body weight, and serum albumin levels, and could serve as a convenient screening mechanism to predict the incidence rate of nutrition-related morbidity and mortality in cancer patients." (PMID 35096932, 2021). "Cancer-related inflammation has been dubbed the 7th hallmark of cancer, and the systemic inflammatory response (SIR) is measured using cellular (whole white cell counts, neutrophils, lymphocytes, and platelets), and humoral (C-reactive protein (CRP) and albumin) components." (PMID 32865623, 2021). "Therefore, these 3 mechanisms can reduce the production of albumin and explain why low preoperative albumin levels can be regarded as a marker of systemic inflammation and a poor prognostic factor for the survival of cancer patients." (PMID 34232194, 2021). "In addition, gastrointestinal disease type was not linked to SARC-F ≥4 points as a significant factor, while age, gender, serum albumin, lymphocyte count, CRP, and the presence of advanced cancer were significant factors linked to SARC-F ≥4 points in the multivariate analysis." (PMID 34575208, 2021). "Therefore, lymphocytes combined with serum albumin can predict the prognosis of cancer patients." (PMID 32026332, 2021).
cancer (continued). "Thus, albumin level is also a useful marker for evaluating clinical outcomes in cancer." (PMID 34284775, 2021). "Moreover, some scoring systems based on circulating blood cell counts and albumin concentration have been also reported to predict cancer patients’ prognosis, such as the Glasgow prognostic score (GPS), systemic inflammation score (SIS), and prognostic nutritional index (PNI)." (PMID 34360768, 2021). "Hence, we determined the predictive value of CRP and albumin (alone or combined) in older cancer patients and determined whether these biomarkers added value to a clinical prognostic model." (PMID 34944774, 2021). "Albumin, which constitutes up to 60% of plasma, is produced in the liver, reflects the nutritional status, is regulated by inflammatory cytokines and may play crucial roles in tumorigenesis and cancer progression." (PMID 34355011, 2021). "In addition, there were interactions between AGR and age, cancer type, and ALB." (PMID 34568033, 2021). "Combining both markers, the albumin to D-dimer ratio (ADR) may reflect the overall inflammation, nutrition, and blood coagulation situation of cancer patients simultaneously, with improved accuracy compared to albumin and D-dimer alone; however, only a few data on this subject are available." (PMID 34239566, 2021). "In addition, serum albumin levels provide useful prognostic significance in cancer." (PMID 34526045, 2021). "Serum ALB may indicate the general status as well as the amount of lean tissue of cancer patients." (PMID 34221991, 2021). "Therefore, GNRI combined with serum albumin and body weight may be a better predictor of patients with cancer cachexia than serum albumin alone." (PMID 34585849, 2021). "In addition to its potential utility for chronic pulmonary infections, this albumin-fusion strategy may represent a promising approach for developing novel adjuvants in cancer prevention and therapeutic vaccines." (PMID 32382128, 2021). "An improvement in albumin levels while on treatment may represent better cancer control." (PMID 34660664, 2021). "Therefore, human serum albumin is suitable as drug carrier for cancer treatment." (PMID 33407570, 2021). "Thus, D-dimer and albumin may play an important role in selecting patients for adjuvant anti-cancer therapy." (PMID 32771026, 2020). "PNI, which calculated as 10 × baseline serum albumin (g/dL) + 0.005 × baseline absolute lymphocyte count (cells/mm3), is used to evaluate the immune-nutritional status and may influence the prognosis of cancer patients." (PMID 33344090, 2020). "Some have concluded that this is antiquated thinking and ignores the fact that albumin is a negative acute phase reactant and that cancer can be considered as an inflammatory condition, and this may in part explain the prognostic value of albumin in patients with cancer." (PMID 32708140, 2020). "Because Cav-1 may be critical for albumin uptake in tumors and perhaps determine how the patients respond to albumin bound drug, such as cisplatin; it is also verified that over-expressed Cav-1 enhanced the sensitivity to nab-paclitaxel in cancer cell lines and mouse xenograft models." (PMID 31901898, 2020). "In addition, the findings of some studies revealed that serum albumin level might be related to the survival outcomes of patients with cancer, such as ovarian cancer and endometrial cancer." (PMID 32456707, 2020). "Finally, although the three GPSs were used in this study, the cutoff values of the CRP and albumin levels were derived from cancer patients, which may lead to their failure to achieve an optimal predictive value for AMI." (PMID 32355581, 2020). "However, this study is, to our knowledge, the first to examine the association between a preoperative albumin, a nutritional risk tool (MUST), body composition, and systemic inflammation in a large number of patients undergoing surgery for primary operable cancer." (PMID 32708140, 2020).